WASIR1 (WASH and IL9R antisense RNA 1)
Synonyms: NCRNA00286B
Gene: Long non-coding RNA gene on chromosome X (156,014,615 to 156,016,885, reverse strand). Ensembl gene ENSG00000185203.
Diseases named in the same sentence as WASIR1 in open-access papers:
WASIR1 is named in the same sentence as 1 disease in open-access papers, as found by Europe PMC text mining. Sharing a sentence is not in itself a finding about the gene and the disease. The quoted sentences say what the papers report.
tumor (1 paper, 2023). "After analyzing the single-cell dataset, it was discovered that IQGAP3, KIF4A, and WASIR1 were expressed in immune cells, indicating their potential involvement in regulating the tumor immune microenvironment in PCa." (PMID 37370891, 2023). "IQGAP3 was expressed in tumor cells, T cells, and monocytes, while WASIR1 was primarily expressed in mast cells." (PMID 37370891, 2023).